TWIST1 (twist family bHLH transcription factor 1)
Diseases named in the same sentence as TWIST1 in open-access papers (continued):
Sharing a sentence is not in itself a finding about the gene and the disease.
gastric cancer (continued). "Immunohistochemistry and statistical analysis demonstrated the relevance of PDCD4 and TWIST1 existed in gastric carcinoma." (PMID 25144746, 2014). "Recently, miR-223, overexpressed in metastatic gastric cancer cells, was also found to be induced by TWIST1." (PMID 23741524, 2013). "Previous studies demonstrate that Twist1 expression is up-regulated in gastric cancer with poor clinical outcomes." (PMID 24204899, 2013). "TWIST1 depletion in other cancers such as prostate and gastric carcinoma also counteract the EMT program." (PMID 22272264, 2012). "Recently, accumulating studies have shown that Twist1 was overexpressed in a variety of solid cancers including breast, prostate and gastric carcinomas rendering Twist1 as a potential oncogene in tumorigenesis." (PMID 22245869, 2012). "Increased expression of Twist1 in gastric cancer CAFs contributes to gastric cancer progression and worse patient survival while its increased expression in NFs can drive CAF marker expression and invasive features of gastric cancer cells both in vivo and in vitro." (PMID 37143134, 2023). "The inhibition of EMT by FAT4 may be mediated by levels of β-catenin followed by downregulation of Twist1 expression, as confirmed in a previous gastric cancer study." (PMID 35132327, 2022). "MiR-16-1-3p mediates TWIST1 to inhibit the malignant potential of gastric cancer cells." (PMID 34141611, 2021). "High expression of CMTM3 might correlate with favorable prognosis in gastric cancer, which not only inhibits the EGF-mediated tumorigenicity by promoting Rab5 activity, but also suppresses metastasis of gastric cancer via the STAT3/Twist1/EMT pathway." (PMID 33282744, 2020). "implied that miR-16-1-3p played an important role in gastric cancer by directly targeting Twist1 and suppressing Twist1-EMT pathways, and might also serve as available therapeutic targets for EMT process in other tumor types." (PMID 33643915, 2020). "Our bioinformatics analysis showed that LUADT1 may form strong base pairing with miR-15a-3p, which can target Twist1 to suppress gastric cancer." (PMID 31842825, 2019). "HMGA2 could promote vasculogenic mimicry and tumor aggressiveness by upregulating Twist1 in gastric carcinoma." (PMID 31249473, 2019). "In parallel, Twist1 expression was correlated with fibroblast activation in gastric cancer." (PMID 29041931, 2017). "Twist1 was recently reported to be a key regulator of CAFs in gastric cancer, but its role in other types of cancer remains unclear, especially for esophageal squamous cell carcinoma (ESCC)." (PMID 29029429, 2017). "In addition, a key EMT transcriptional factor, Twist1, was shown to be responsible for MARCKS action on CAF characteristics, similar to that Twist1 induced the transformation of normal fibroblasts in gastric cancer." (PMID 27081703, 2016). "Meanwhile, we also found that ectopic expression of miR-186 could affect cell proliferation, invasion and migration of gastric cancer partially via targeting the expression of Twist1." (PMID 27835599, 2016). "In conclusion, miR-186 affects the proliferation, invasion and migration of human gastric cancer by inhibition of Twist1, and could be a tumor suppressor in GC development." (PMID 27835599, 2016). "Twist1 overexpression is frequently observed in various cancers including gastric cancer (GC)." (PMID 26695186, 2015). "In addition, there are limited data on the role of CPEB1 in ferroptosis, just one study reported that CPEB1 promotes ferroptosis susceptibility in gastric cancer by suppressing TWIST1 expression 25, which does not apply to pancreatic cancer." (PMID 38904009, 2024). "However, the more molecular mechanisms of Twist1 involved in the development of gastric cancer remain unclear." (PMID 27835599, 2016). "To figure out the significance of miR-186 and Twist1 in the development of gastric cancer, firstly, we detected and analyzed the expression of miR-186 and Twist1 in cancer samples of GC and their paired normal samples." (PMID 27835599, 2016).
gastric cancer (continued). "Moreover, Snail and Twist1 are overexpressed in gastric carcinoma." (PMID 27121055, 2016). "Aberrant DNA methylation at the CGI promoter in human Twist1 has been frequently detected in primary cancers including of gastric cancer (GC)." (PMID 26695186, 2015). "Besides, Twist1 is suggested to be involved in progression of human gastric cancer." (PMID 24204899, 2013). "In gastric cancer, research has shown that PAQR3 facilitates the interaction between Twist1 and the ubiquitination ligase BTRC, accelerating Twist1 degradation and ultimately inhibiting epithelial–mesenchymal transition (EMT) and metastasis." (PMID 40723340, 2025). "Hp cytotoxin-associated gene A (Cag A) reduced the expression of E-cadherin and enhanced the expression of vimentin and TWIST1, thereby describing new EMT signaling pathways in gastric cancer cell lines." (PMID 39941895, 2025). "In this study, we systematically delineated the transcriptional regulatory landscape of THY1 in gastric cancer by identifying six robust putative regulators—PRRX1, TWIST1, SNAI2, MEIS3, VENTX, and EGR2—through an integrative multicohort approach." (PMID 40476057, 2025). "Immunohistochemistry was used to detect the expression of FAP, CD10, and GPR77 in CAFs; the EMT markers (N-cadherin, Snail1, and Twist1) and the CSC markers (ALDH1, CD44, and LGR5) in gastric cancer cells." (PMID 37277751, 2023). "In gastric cancer cells, EMP3 can act as a downstream effector of TWIST1 and TWIST2 and participate in the EMT of gastric cancer." (PMID 36217151, 2022). "The overexpression of Twist1 and MMP-9 affects the overall survival and metastasis of human gastric carcinoma patients." (PMID 33567682, 2021). "To assess SCD1 activation in gastric cancer at a larger scale, we performed immunofluorescent staining for SCD1, Twist1 and Ki67 of paraffin-embedded tissue sections from MKN45-SCD1 xenografts and control ones." (PMID 32726752, 2020). "In gastric cancer, EMP3 has been suggested as a downstream effector of TWIST1/2 and a regulator of EMT." (PMID 32857809, 2020). "The downregulation of miR-186 and its connection with Twist1 and HIF-1α has been recognized as antitumor growth biomarker in gastric cancer." (PMID 32099601, 2019). "In gastric cancer and NSCLC tissues, miRNA-15a was significantly downregulated, while Twist1 gene and its regulated proteins were significantly increased." (PMID 31061821, 2019). "Cordycepin reduced the expression of the EMT factors in 72 melanoma patient samples comprising HMGA2, Twist1, and ZEB1, and the inhibition of HMGA2 sensitized gastric cancer cells to chemotherapy treatment." (PMID 29853899, 2018). "This STAT-3/Twist1 axis has also been verified in hepatocellular carcinoma cells and the Notch1/STAT3/Twist1 signaling axis has been identified in gastric cancer." (PMID 28099910, 2017). "Lately, we found that PAQR3 is able to regulate ubiquitination and degradation of Twist1, a master regulator of EMT in gastric cancer cells." (PMID 28903314, 2017). "In gastric cancers, IL6 activates fibroblastic Twist1, and the resulting CAFs secrete the chemokine CXCL12 in a Twist1‐dependent manner." (PMID 28544627, 2017). "We found that knockdown of CMTM3 promoted cell migration, invasion and tumor metastasis via the STAT3/Twist1/EMT pathway, which will be helpful to understand the pathogenesis of gastric cancer." (PMID 27121055, 2016). "In summary, we demonstrate that H. pylori CagA induce TWIST1 expression and EMT in gastric cancer cells by regulating PDCD4." (PMID 25144746, 2014). "For all of our validated genes of interest (VAV3, TWIST1 and DKK3), it has previously been established that the level of the mRNA expression is representative for its protein level, in pulmonary fibrosis, gastric cancer and various cell lines." (PMID 20976069, 2010).
gastric cancer (continued). "Similarly, the sex-determining region Y-box protein 5–Twist family BHLH transcription factor 1 pathway, a master regulator of EMT in prostate and gastric cancers, was significantly upregulated in ST6GAL1-overexpressing SW48 cells." (PMID 39937175, 2025). "•TWIST1 and SNAI2 were validated as key regulators of THY1 in gastric cancer." (PMID 40476057, 2025). "Another study also showed that the knockdown of TWIST, an EMT‐triggering transcription factor, hinders EMT and CTPS expression in gastric cancer cells; however, our results indicated that the knockdown of TWIST1 did not impact TGF‐β‐induced CTPS expression." (PMID 39030877, 2024). "In gastric cancer, resistance to the vascular endothelial growth factor receptor 2 inhibitor apatinib is mediated by the expression of COL1A2, which, in turn, was regulated at the transcriptional level by EP300 and TWIST1." (PMID 38139368, 2023). "Both miR-15a-3p and miR-16-1-3p target two conserved sites in the 3′-UTR of Twist1 to reduce the mRNA and protein levels of biomarkers, including N-cadherin, α-SMA, fibronectin, and MMP9, so as to attenuate the migration and invasion of gastric cancer cells." (PMID 35805066, 2022). "Taken together, these findings suggested that Twist1 and Arpc3 mRNAs are positively regulated by MYOF and that MYOF might promote the motility of gastric cancer cells." (PMID 36147922, 2022). "Induced expression of ETS2, Twist1 and Siah2 was found in gastric cancer biopsies compared with noncancerous gastric tissue." (PMID 33825941, 2021). "In the gastric cancer cells AGS, Kato III and MKN45, H. pylori infection induced an expression of Siah2, in a E26 transformation-specific sequence 2 (ETS2)- and Twist-related protein 1 (Twist1)-dependent manner, which was accompanied by increased invasiveness and migration." (PMID 33825941, 2021). "Although CXCL12 promotes the expression of Snail1 and Twist1 in glioblastoma cancer cells, and of Snail1 in human oral squamous cell carcinomas, no reports show CXCL12‐induced expression of Snail1 or Twist1 in tumour cells of gastric cancers." (PMID 28544627, 2017). "We previously reported that metastasis-associated in colon cancer-1 (MACC1) contributed to the vasculogenic mimicry in gastric cancer (GC), but it remains unknown whether MACC1 promotes endothelium-dependent angiogenesis of GC and whether TWIST1 is involved in this process." (PMID 27280289, 2016). "In the present study, it was observed that IGF-I induced EMT and upregulated ZEB2, but not ZEB1, Twist1 or Twist2, in gastric cancer BGC-823 cells." (PMID 25435948, 2015). "In gastric cancer, VIM, which has been known to be a methylation marker, was also hypermethylated, and it centered in the network interaction with other proteins, such as PDGF complex and TWIST1." (PMID 24842468, 2014). "Together, these findings provide experimental evidence supporting TWIST1 and SNAI2 as direct regulators of THY1, integrating bioinformatic predictions and experimental insights into a cohesive model of THY1 transcriptional regulation in the context of gastric cancer." (PMID 40476057, 2025). "This study provides experimental evidence of TWIST1 and SNAI2 binding to the THY1 regulatory regions in a gastric cancer cell line with high THY1 expression, supporting the hypothesis that these transcription factors may act as key regulators of THY1 expression in this context." (PMID 40476057, 2025). "In addition, FAT4 might decrease the levels of β-catenin and then downregulate Twist1 expression to suppress CRC development, as demonstrated in the study of gastric cancer conducted by Cai." (PMID 30832706, 2019). "It is therefore necessary to further determine other upstream activators of the STAT3/Twist1/EMT pathway in the CMTM3-knockdown system and to investigate the function of CMTM3 on the expression, stabilization, internalization and degradation of RTKs in gastric cancer cells." (PMID 27121055, 2016).
hepatocellular carcinoma (86 papers, 2011 to 2026). A malignant tumor that arises from hepatocytes. "In the present study, hepatoma cells treated with the TIP60 inhibitor TH1834 or transfected with the TWIST1 AC2 mutant showed loss of acetylation and nuclear localization of both TWIST1 and SPZ1." (PMID 30154425, 2019). "Intriguingly, overexpression of TWIST1 has been linked to invasion and metastasis in hepatocellular carcinoma and oesophageal cancer." (PMID 21731750, 2011). "In our study, the data showed that the mRNA level of TWIST1 was upregulated in PCK1-deficient hepatoma cells, suggesting that PCK1 may transcriptionally inhibit TWIST1 by O-GlcNAcylation of KAT5." (PMID 34650217, 2021). "Further studies are needed to verify whether TWIST1 can be acetylated by KAT5 in PCK1-deficient hepatoma cells." (PMID 34650217, 2021). "MYC and Twist1 cooperate to drive metastasis by initiating crosstalk between hepatocellular carcinoma and innate immunity." (PMID 36639679, 2023). "Overexpression of Twist1, one of the epithelial-mesenchymal transition-transcription factors (EMT-TFs), is associated with hepatocellular carcinoma (HCC) metastasis." (PMID 37495969, 2023). "Previous reports validated the transcriptional regulation of SNAIL and TWIST1 by miR-370-3p in hepatocellular carcinoma, thereby suppressing metastasis, as well as CDH1 by miR-421 in HNSCC, thereby promoting cell invasion and proliferation." (PMID 36686733, 2022). "PPI impaired VM formation by blocking the PI3k-Akt-Twist1-VE-cadherin pathway hepatocellular carcinoma." (PMID 35321317, 2022). "For example, MYBL1 promoted the hepatocellular carcinoma growth and metastasis via upregulation of TWIST1." (PMID 34691188, 2021). "Various studies have reported that Twist (Twist1,2) acts as a pro-metastatic agent in various cancer including breast, prostate, bladder, hepatocellular carcinoma and so on." (PMID 34627167, 2021). "Twist1 ectopically overexpressed in another hepatocellular carcinoma cell line, Hep3B, was also inhibited by GCB treatment." (PMID 33567682, 2021). "The relationship between LCN2 and Twist1 has been previously reported that the LCN2/Twist1 signaling pathway negatively regulates EMT in hepatocellular carcinoma." (PMID 32272958, 2020). "As shown in the previous study, SOX12, a direct target of FOXQ1, promotes hepatocellular carcinoma (HCC) metastasis by upregulating Twist1 and FGFBP116." (PMID 30858360, 2019). "Expression of Twist1 is associated with enhanced tumor microvessel vasculature and VEGF expression in hepatocellular carcinomas." (PMID 29416649, 2018). "TWIST1 downregulates miR-26b-5p in hepatocellular carcinoma by binding to its promotor region, thereby unchecking Smad1 expression and deregulating BMP4/Smad1 signaling, which promotes EMT." (PMID 29112161, 2017). "TWIST1 upregulates 18 miRNAs in hepatocellular carcinoma cells, among them miR-27a-3p which targets VE-cadherin and suppresses EMT and VM." (PMID 29112161, 2017). "Bcl-2 and Twist1 can be coactivated by hypoxia in hepatocellular carcinoma to promote tumor cell metastasis and vasculogenic mimicry, but their function in oral squamous cell carcinoma (OSCC) remains undefined." (PMID 28032603, 2017). "TWIST1 is a transcription factor involved in EMT regulation, and it was reported that the Bcl-2/TWIST1 complex facilitates VM in hepatocellular carcinoma." (PMID 25895023, 2015). "We found that the EMT factor Twist1 induced the expression of VE-cadherin to promote VM in hepatocellular carcinoma." (PMID 25200065, 2014). "In hepatoma, Twist1 can promote vimentin expression, and it has been verified that Twist1 is combined with a circular RNA, the promoter region of CUL2 (Cullin-2), and promotes the mRNA of vimentin by adsorbing the microRNA targeting vimentin degradation, resulting in EET." (PMID 33397409, 2021).
hepatocellular carcinoma (continued). "Importantly, we found that O-GlcNAcylation increased KAT5 stability, thereby inducing epigenetic activation of TWIST1, associated with the acquisition of a metastatic phenotype in PCK1-deficient hepatoma cells." (PMID 34650217, 2021). "In hepatocellular carcinoma, Twist1 suppresses E-cadherin expression and induces EMT changes." (PMID 30973923, 2019). "Therefore, SPZ1 appeared to interact with TWIST1 in cultured hepatoma cells, SPZ1 transgenic mice, and HCC tumor specimens." (PMID 30154425, 2019). "Additionally, the nuclear expression of Bcl-2 and Twist1 is correlated with poor survival in hepatocellular carcinoma." (PMID 28032603, 2017). "For example, SOX5 promoted EMT process by regulation of Twist1 in hepatocellular carcinoma." (PMID 28335789, 2017). "Twist1 can promote migratory and invasive effects on hepatocellular carcinoma by inducing EMT." (PMID 27027434, 2016). "Importantly, we uncovered a novel mechanism that O-GlcNAcylation of KAT5, as a transcriptional regulator, epigenetically activates TWIST1 via enhancing histone H4 acetylation on the TWIST1 promoter, thereby inhibiting E-cadherin expression in PCK1-deficient hepatoma cells." (PMID 34650217, 2021). "TRABID has also been shown to regulate the expression levels of the transcriptional regulator Twist1 in hepatocellular carcinoma (HCC)." (PMID 33435370, 2021). "We generated an autochthonous transgenic mouse model whereby conditional expression of MYC and Twist1 enables hepatocellular carcinoma (HCC) to metastasize in >90% of mice." (PMID 31933479, 2020). "While Sun et.al indicated that Twist1 contributed to EMT process through down-regulation of E-cadherin expression in hepatocellular carcinoma (HCC)." (PMID 26842802, 2016). "Our previous studies have implicated transcriptional factors Twist1 and epithelial–mesenchymal transition (EMT)in the formation of VM by human hepatocellular carcinoma (HCC) cells in vivo and in vitro." (PMID 23815612, 2013). "Furthermore, the Bcl-2/Twist1 complex facilitates the nuclear transport of Twist1 and leads to transcriptional activation of a wide range of genes that may increase the tumor cell plasticity, metastasis and VM formation of hepatocellular carcinoma." (PMID 24179490, 2013). "Three previously underreported mechanistic dimensions were identified: TWIST1 downregulation and FZD7 binding in hepatocellular carcinoma, and downregulation of CEA, CEAM6, MMP2F, and MMP9F in colorectal cancer lines." (PMID 42075866, 2026). "In hepatocellular carcinoma, LCN2 inhibits the transcriptional initiation of Twist1 to moderate EMT and suppress metastasis." (PMID 40109857, 2025). "In hepatocellular carcinoma (HCC), for instance, Twist1 overexpression activated the pentose phosphate pathway, glycolysis, and several other metabolic pathways." (PMID 37784111, 2023). "For instance, the SE-induced seRNA HCCL5 promotes hepatocellular carcinoma (HCC) cells viability, migration and epithelial-to-mesenchymal transition (EMT) by upregulating Snail, Slug, ZEB1, and Twist1." (PMID 35461306, 2022). "Moreover, Twist1 relied on TP-induced metabolic reprogramming to promote hepatocellular carcinoma (HCC) metastasis and VM formation mediated by VE–Cad, VEGFR1, and VEGFR2 in vitro and in vivo." (PMID 30674871, 2019). "Twist1, a transcriptional regulatory factor of EMT, is an important factor that induces EET in hepatocellular carcinoma(HCC), but the upstream signal of Twist1 is unclear." (PMID 30081924, 2018). "Moreover, in hepatocellular carcinoma (HCC), miR-675 has been shown to directly promote E-cadherin expression through directly targeting of Twist1 in HCC cells." (PMID 28430163, 2017). "The reason for the expression of VE-cadherin in non-endothelial cells is mostly unclear, but in hepatocellular carcinoma (HCC) it may be due the to nuclear localization of Twist1." (PMID 28320399, 2017).